PLAAT5 (phospholipase A and acyltransferase 5)
Description:
Exhibits both phospholipase A1/2 and acyltransferase activities. Shows phospholipase A1 (PLA1) and A2 (PLA2) activity, catalyzing the calcium-independent release of fatty acids from the sn-1 or sn-2 position of glycerophospholipids. Shows N-acyltransferase activity, catalyzing the calcium-independent transfer of a fatty acyl group at the sn-1 position of phosphatidylcholine (PC) and other glycerophospholipids to the primary amine of phosphatidylethanolamine (PE), forming N-acylphosphatidylethanolamine (NAPE), which serves as precursor for N-acylethanolamines (NAEs).
Synonyms: iNAT; HRSL5; HRASLS5; HRLP5; PLAAT-5; RLP1
Tractability: Small molecule: a high-quality ligand is known. PROTAC: a small molecule that binds it is known.
Target class: Enzyme; Transferase
Gene: Protein-coding gene on chromosome 11 (63,461,404 to 63,491,219, reverse strand). Ensembl gene ENSG00000168004.
Subcellular location: Cytoplasm, cytosol
Subcellular location (Human Protein Atlas): Cytosol; Nucleoplasm
Pathways (Reactome):
Metabolism: Acyl chain remodelling of PE
Gene Ontology:
Molecular function: acyltransferase activity, transferring groups other than amino-acyl groups; phospholipase A1 activity; phospholipase A2 activity; protein binding
Biological process: N-acylphosphatidylethanolamine metabolic process
Cellular component: cytoplasm; cytosol
Genetic constraint (gnomAD): Loss-of-function variants: 24 observed, 20.87 expected, observed/expected ratio (o/e) 1.15, 90% interval 0.83 to 1.61. The upper end of that interval is the gene's LOEUF score, 1.61, which puts it in group 6 of 6, group 1 being the genes least tolerant of losing a copy. Missense variants: 326 observed, 289.55 expected, observed/expected ratio (o/e) 1.13, 90% interval 1.03 to 1.23. Synonymous variants: 109 observed, 114.21 expected, observed/expected ratio (o/e) 0.95, 90% interval 0.82 to 1.12.
Homologues: Orthologues: chimpanzee PLAAT5 (97% identical), macaque PLAAT5 (94% identical), rabbit PLAAT5 (76% identical), pig PLAAT5 (75% identical), dog PLAAT5 (73% identical), mouse Plaat5 (72% identical), rat Plaat5 (70% identical), zebrafish lratb.2 (16% identical). Paralogues in human: PLAAT3 (28% identical), PLAAT4 (27% identical), PLAAT2 (27% identical), PLAAT1 (22% identical), LRAT (17% identical), LRATD2 (16% identical), LRATD1 (11% identical).
Diseases named in the same sentence as PLAAT5 in open-access papers:
PLAAT5 is named in the same sentence as 8 diseases in open-access papers, as found by Europe PMC text mining. Sharing a sentence is not in itself a finding about the gene and the disease. The quoted sentences say what the papers report.
brain ischemia (1 paper, 2025). Diminished or absent blood supply to the brain caused by obstruction (thrombosis or embolism) of an artery resulting in neurologic damage. "cPLA2ε and PLAAT5 function as N-acyltransferases and produce anti-inflammatory NAEs to mitigate pathological conditions, including psoriasis, brain ischemia, and testicular inflammation." (PMID 40244184, 2025).
colon cancer (1 paper, 2023). "The results showed that the expression levels of ACSL6, CYP19A1, LRP2, OSBPL3 and SLCO1A2 were considerably increased, while those of ACOX1, FABP4, PLAAT5, PPARGC1A and TNFAIP8L3 were decreased in colon cancer." (PMID 38045683, 2023).
PLAAT5 also shares sentences with these, for which no sentence is quoted: breast carcinoma (2 papers); Arrhythmia (1); colon adenocarcinoma (1); colorectal cancer (1); psoriasis (1); tumor (1).